DPF3 (double PHD fingers 3)
Description:
Belongs to the neuron-specific chromatin remodeling complex (nBAF complex). During neural development a switch from a stem/progenitor to a post-mitotic chromatin remodeling mechanism occurs as neurons exit the cell cycle and become committed to their adult state. The transition from proliferating neural stem/progenitor cells to post-mitotic neurons requires a switch in subunit composition of the npBAF and nBAF complexes. As neural progenitors exit mitosis and differentiate into neurons, npBAF complexes which contain ACTL6A/BAF53A and PHF10/BAF45A, are exchanged for homologous alternative ACTL6B/BAF53B and DPF1/BAF45B or DPF3/BAF45C subunits in neuron-specific complexes (nBAF). The npBAF complex is essential for the self-renewal/proliferative capacity of the multipotent neural stem cells. The nBAF complex along with CREST plays a role regulating the activity of genes essential for dendrite growth (By similarity). Muscle-specific component of the BAF complex, a multiprotein complex involved in transcriptional activation and repression of select genes by chromatin remodeling (alteration of DNA-nucleosome topology). Specifically binds acetylated lysines on histone 3 and 4 (H3K14ac, H3K9ac, H4K5ac, H4K8ac, H4K12ac, H4K16ac). In the complex, it acts as a tissue-specific anchor between histone acetylations and methylations and chromatin remodeling. It thereby probably plays an essential role in heart and skeletal muscle development. [Isoform 2]: Acts as a regulator of myogenesis in cooperation with HDGFL2. Mediates the interaction of HDGFL2 with the BAF complex. HDGFL2-DPF3a activate myogenic genes by increasing chromatin accessibility through recruitment of SMARCA4/BRG1/BAF190A (ATPase subunit of the BAF complex) to myogenic gene promoters.
Synonyms: BAF45C; CERD4; cer-d4; FLJ14079; SMARCG3
Tractability: PROTAC: UniProt records ubiquitination sites on it; ubiquitination databases record sites on it; its protein half-life has been measured.
Gene: Protein-coding gene on chromosome 14 (72,609,034 to 72,894,101, reverse strand). Ensembl gene ENSG00000205683.
Subcellular location: Nucleus
Subcellular location (Human Protein Atlas): Nucleoplasm
Pathways (Reactome):
Chromatin organization: Formation of neuronal progenitor and neuronal BAF (npBAF and nBAF); Formation of the canonical BAF (cBAF) complex
Developmental Biology: Regulation of MITF-M-dependent genes involved in pigmentation
Gene expression (Transcription): Regulation of endogenous retroelements by Piwi-interacting RNAs (piRNAs)
Gene Ontology:
Molecular function: zinc ion binding
Biological process: chromatin remodeling; positive regulation of cell differentiation; positive regulation of double-strand break repair; positive regulation of myoblast differentiation; regulation of G0 to G1 transition; regulation of G1/S transition of mitotic cell cycle; regulation of mitotic metaphase/anaphase transition; regulation of nucleotide-excision repair; regulation of transcription by RNA polymerase II; nervous system development
Cellular component: nucleoplasm; brahma complex; chromatin; nBAF complex; nucleus; SWI/SNF complex
Genetic constraint (gnomAD): Loss-of-function variants: 18 observed, 54.35 expected, observed/expected ratio (o/e) 0.33, 90% interval 0.23 to 0.49. The upper end of that interval is the gene's LOEUF score, 0.49, which puts it in group 2 of 6, group 1 being the genes least tolerant of losing a copy. Missense variants: 403 observed, 492.69 expected, observed/expected ratio (o/e) 0.82, 90% interval 0.75 to 0.89. Synonymous variants: 188 observed, 184.15 expected, observed/expected ratio (o/e) 1.02, 90% interval 0.91 to 1.15.
Homologues: Orthologues: mouse Dpf3 (99% identical), dog DPF3 (99% identical), pig DPF3 (97% identical), guinea pig DPF3 (97% identical), tropical clawed frog dpf3 (80% identical), chimpanzee DPF3 (78% identical), macaque DPF3 (78% identical), rat Dpf3 (78% identical), rabbit DPF3 (77% identical), zebrafish dpf3 (72% identical), Drosophila melanogaster d4 (44% identical), Caenorhabditis elegans dpff-1 (35% identical), and 1 more. Paralogues in human: DPF1 (71% identical), DPF2 (64% identical), KAT6A (22% identical), KAT6B (22% identical), RSF1 (22% identical), KAT7 (18% identical), KAT5 (15% identical), KAT8 (13% identical), PHF10 (8% identical).
Diseases named in the same sentence as DPF3 in open-access papers:
DPF3 is named in the same sentence as 25 diseases in open-access papers, as found by Europe PMC text mining. Sharing a sentence is not in itself a finding about the gene and the disease. The quoted sentences say what the papers report.
breast carcinoma (5 papers, 2005 to 2025). "Polymorphisms in the 5' region of DPF3 were associated with increased risk of breast cancer development, lymph node metastases, age of onset, and tumor size in women of European ancestry." (PMID 16109180, 2005). "Here, we report variants in DPF3, identified through a large-scale, genome-wide association study, that are associated with increased breast cancer risk, lymph node metastases, decreased age of onset, and increased tumor size." (PMID 16109180, 2005). "Our study in women of European ancestry identified significant associations between polymorphisms in DPF3 and breast cancer susceptibility, lymph node metastases, earlier age of onset, and tumor size." (PMID 16109180, 2005). "Herein, we describe variations in intron 1 of DPF3 on chromosome 14q24.3-q31.1 that are associated with increased risk of breast cancer, lymph node metastases, earlier age of diagnosis, and tumor size." (PMID 16109180, 2005). "This large-scale association study suggests that genetic variation in DPF3 contributes to breast cancer susceptibility and severity." (PMID 16109180, 2005). "Association of the DPF3 polymorphisms with traits of interest in discovery breast cancer cases." (PMID 16109180, 2005). "While the current study suggests that variants in DPF3 intron 1 are associated with increased breast cancer risk, the possible mechanism by which these variants predispose to breast cancer are purely speculative." (PMID 16109180, 2005). "The histone reader protein DPF3 has been shown to induce proliferation of breast cancer cells (PMID: 31076105)." (PMID 34354115, 2021). "Additional experimental studies will be required to precisely elucidate the role of DPF3 in breast cancer etiology and progression." (PMID 16109180, 2005). "DPF3, a chromatin remodeling cofactor significantly downregulated in breast cancer tissue, promoting the proliferation of breast cancer cells, has been suggested as a novel therapeutic target for breast cancer therapy." (PMID 37444571, 2023). "While three independent samples from the current study support the observed associations, additional studies are needed to verify the results and to further characterize the gene in order to fully understand the role of DPF3 in the etiology and progression of breast cancer." (PMID 16109180, 2005).
Alzheimer disease (2 papers, 2005 to 2015). A progressive, neurodegenerative disease characterized by loss of function and death of nerve cells in several areas of the brain leading to loss of cognitive function such as memory and language. "PSEN1 encodes a protein that regulates the processing of amyloid precursor protein (APP) and is mutated in familial forms of Alzheimer’s disease while DPF3 function is associated with the BAF chromatin remodeling complex to promote transcription during development." (PMID 25969726, 2015). "More recently, DPF3 has been identified by microarray analysis as a transcription factor that may play a role in the pathogenesis of incipient Alzheimer's disease." (PMID 16109180, 2005).
kidney cancer (2 papers, 2022 to 2025). Primary or metastatic malignant neoplasm involving the kidney. "In this study, we demonstrate that DPF3a, the short isoform of DPF3, promotes kidney cancer cell migration both in vitro and in vivo, consistent with the clinical observation that DPF3a is significantly upregulated in ccRCC patients with metastases." (PMID 35945219, 2022).
lung carcinoma (2 papers, 2022 to 2025). "In PhenoScanner, 6 out of 12 hub genes (IRAK2, MECOM, ASB4, CDC42BPA, DPF3 and TMEM67) have revealed an association with lung related traits and lung cancer." (PMID 36194576, 2022). "Other COPD- hub genes (CDC42BPA, ASB4, DPF3 and TMEM67) are were also associated with lung function related traits and lung cancer." (PMID 36194576, 2022). "The DPF3 gene is associated with COPD and squamous cell carcinoma, lung cancer." (PMID 36194576, 2022). "Additional COPD hub genes like SREK1, TMEM67, CDC42BPA, DPF3, and ASB4 were identified as prognostic markers in lung cancer, which is reported in 1% of COPD patients." (PMID 36194576, 2022). "Furthermore, DDX3Y and DPF3 staining in normal lung tissues were negative but DDX3Y was higher in lung cancer tissue but not DPF3." (PMID 36194576, 2022). "Interestingly, we have also identified that the expression status of other COPD hub genes like SREK1, TMEM67, CDC42BPA, DPF3, and ASB4 improves the survival duration of lung cancer patients, hence they may act as potential molecular drug targets and/or biomarkers for both COPD and/or lung cancer." (PMID 36194576, 2022).
cardiac hypertrophy (1 paper, 2016). "To further investigate the role of DPF3 in pathological cardiac hypertrophy, we studied cases of HCM and pressure overload related hypertrophy resulting from AS." (PMID 26582913, 2016). "We show that DPF3, in particular DPF3a, is significantly up-regulated in pathologic cardiac hypertrophy in patients with HCM as well as AS." (PMID 26582913, 2016).
clear cell renal cell carcinoma (1 paper, 2022). "DPF3, a component of the SWI/SNF chromatin remodeling complex, has been associated with clear cell renal cell carcinoma (ccRCC) in a genome-wide association study." (PMID 35945219, 2022). "The functional role of DPF3, a component of the SWI/SNF chromatin remodelling complex associated with clear cell renal cell carcinoma (ccRCC), remains unknown." (PMID 35945219, 2022).
glaucoma (1 paper, 2022). Increased pressure in the eyeball due to obstruction of the outflow of aqueous humor. "BOD1L1, RALYL, LDB3, ACAD10, CDK11A, and DPF3 are also associated with glaucoma topical treatments (P < 1 × 10−5)." (PMID 36450729, 2022).
legionellosis (1 paper, 2022). Any disease caused by Legionella bacteria. "‘Legionellosis’ (hsa05134) was mainly enriched by DPF3 cluster." (PMID 36194576, 2022).
male infertility (1 paper, 2023). The inability of the male to effect fertilization of an ovum after a specified period of unprotected intercourse. "Notably, variants within DPF3 have been strongly associated with male infertility and sperm morphology in diverse ethnic groups from the US and China." (PMID 37485336, 2023).
metastatic tumors (1 paper, 2022). "Moreover, in another clinical cohort of ccRCC patients, the expression of DPF3 was found to be significantly higher in metastatic tumors than in primary ones, suggesting a potential role of DPF3 in tumor metastasis." (PMID 35945219, 2022).
prostate carcinoma (1 paper, 2023). A carcinoma that arises from epithelial cells of the prostate gland. "Biased towards African-specific drivers (63 versus 9 shared), many are novel to prostate cancer (18/63), including several putative therapeutic targets (CHD7, DPF3, POLR1B, SETD1B, UBTF, and VPS72)." (PMID 37444571, 2023).
renal cell carcinoma (1 paper, 2022). "Most recently, DPF3 has been found to be particularly essential to the signalling pathways involved in renal cell carcinoma (RCC) oncogenesis by inhibiting apoptosis, as well as promoting cell growth and RCC metastasis." (PMID 36499617, 2022).
Tetralogy of Fallot (1 paper, 2021). A congenital cardiac malformation comprising pulmonary stenosis, overriding aorta, ventricular septum defect, and right ventricular hypertrophy. "The double PHD fingers 3 (DPF3) gene was shown to function in heart development, through a genome-wide association study comparing congenitally malformed hearts exhibiting tetralogy of Fallot and normal hearts." (PMID 34072132, 2021).
tumor (5 papers, 2005 to 2025). "Multiple observations point towards a role of various BAF subunits in tissue-specific tumor prevention, opening the way for investigations on the functional role of other subunits, including DPF3 (BAF45C)." (PMID 24155890, 2013). "In our present study using epithelial tumor cells, we showed that the CT1 peptide comprising the 84 N-terminal amino acids of either the DPF2 or DPF3 protein functions as a dominant-negative mutant." (PMID 28924147, 2017).
cancer (4 papers, 2017 to 2025). A tumor composed of atypical neoplastic, often pleomorphic cells that invade other tissues. "In contrast, only a couple of studies have linked DPF3 to human cancer." (PMID 35945219, 2022). "In contrast, the ten node genes in the mammary glands of the offspring of dams fed the CON diet were linked to changes in the expression of genes indicative of reduced cancer risk (downregulation of DPF3, SNORA41) and improved immune functions (upregulation of ZBP1, ZFP683; downregulation of EGR3)." (PMID 28673325, 2017). "DPF3 is an amyloidogenic IDP that has been identified in many cancer types, as well as in neurogenerative disorders, such as AD and PD." (PMID 36499617, 2022). "DPF3 is also involved in male infertility, colon defects (Hirschsprung’s disease), as well as in many cancer types." (PMID 36499617, 2022). "Double-PHD fingers 3 (DPF3) is a BAF-associated human epigenetic regulator, which is increasingly recognised as a major contributor to various pathological contexts, such as cardiac defects, cancer, and neurodegenerative diseases." (PMID 36499617, 2022). "To explore the distinct function of the two isoforms in regulating cancer cell proliferation, we overexpressed the two isoforms separately in 786-O, one of the first established ccRCC cell lines, in which DPF3 is almost undetectable." (PMID 35945219, 2022).
hematologic malignancies (1 paper, 2013). "The DPF3 expression analysis in hematologic malignancies with activated STAT5 presented here was performed in an effort to understand the mechanisms linking oncogenesis to the interplay of STAT5 activation and regulation of its target genes." (PMID 24155890, 2013). "Expression of DPF3 gene in patients with hematologic malignancies." (PMID 24155890, 2013).
neurodegenerative disease (1 paper, 2022). A disorder of the central nervous system characterized by gradual and progressive loss of neural tissue and neurologic function. "As DPF3 is a metalloprotein and the alteration of metal homeostasis is associated with the development of neurodegenerative diseases, we also investigated the influence of divalent metal cations, namely Cu2+, Mg2+, Ni2+, and Zn2+, on the aggregation mechanisms and properties of each C-TER." (PMID 36499617, 2022). "Assessing the sensitivity of DPF3 to metals will help to elucidate its function in neurodegenerative diseases." (PMID 36499617, 2022).
DPF3 also shares sentences with these, for which no sentence is quoted: asthma (1 paper); atrial fibrillation (1); Chronic Lymphocytic Leukemia (1); hypertrophic cardiomyopathy (1); lung disease (1); lymph node metastases (1); melanoma (1); squamous cell carcinoma (1).